FTO (FTO alpha-ketoglutarate dependent dioxygenase)
Diseases named in the same sentence as FTO in open-access papers (continued):
Sharing a sentence is not in itself a finding about the gene and the disease.
Obesity (continued). "When a BMI ≥30 kg/m2 was used to define obesity and logistic regression models were adjusted for age and gender, addition of an FTO rs1421085 C allele conferred an elevated risk of being obese for both white and African-American participants." (PMID 20502638, 2010). "Given that variants in FTO are associated with human obesity and that Fto mRNA levels appear to be regulated in response to feeding and fasting, its expression was determined in relation to changes in obesity." (PMID 20381893, 2010). "FTO (fat mass and obesity associated) was identified as an obesity-susceptibility gene by several independent large-scale genome association studies." (PMID 21103374, 2010). "Genetic variants in FTO are associated with the obesity phenotype in European and Hispanic populations." (PMID 20858286, 2010). "Sequence variants in the first intron of FTO are strongly associated with human obesity and human carriers of the risk alleles show evidence for increased appetite and food intake." (PMID 20098739, 2010). "The newest study identifying 6 additional obesity predisposing variants in combination with FTO and MC4R explained only 0.84% of the variance in BMI." (PMID 20532202, 2010). "In the recent two years, several genome-wide association (GWA) studies have indicated that the fat mass and obesity associated (FTO) gene has an important genetic effect on BMI and risk of obesity." (PMID 20467478, 2010). "Single nucleotide polymorphisms (SNPs) in the fat mass and obesity associated (FTO) gene are associated with body mass index (BMI) in populations of European descent." (PMID 20502638, 2010). "We genotyped FTO variants rs9939609 in 670 children (332 girls and 338 boys) aged 8-11 years living in Beijing, and analyzed its association with obesity and obesity-related metabolic traits." (PMID 20858286, 2010). "More replication studies about the association between the FTO gene and obesity-related metabolic traits were guaranteed among larger Chinese population." (PMID 20858286, 2010). "Most recently, the FTO gene has been given special attention because of its strong association with obesity in multiple cohorts differing in age." (PMID 20380707, 2010). "We investigated genetic association between a set of obesity related anthropometric measures and 29 common SNPs in the FTO gene." (PMID 20442772, 2010). "Common variants within intron 1 of the fat mass and obesity associated gene (FTO) are strongly and consistently associated with human adiposity." (PMID 20098739, 2010). "Two independent genome-wide association (GWA) studies firstly discovered significant associations of common genetic variants (rs9939609) in the fat mass and obesity-associated (FTO) gene with body mass index (BMI) as a measure of general obesity." (PMID 20377915, 2010). "Murine models initially lent support to FTO itself being the causal gene in the locus; an obesity protective phenotype was observed in the fto knock-out mouse and a similar but lesser effect in the hypomorphic fto missense I367F mutant." (PMID 21124985, 2010). "In conclusion, our findings detected an association between the FTO rs9939609 variant and BMI and risk of obesity among children and adolescents of Chinese ancestry." (PMID 20598163, 2010). "We report here the associations of common FTO variants with these classic and other obesity related anthropometric measures including bicondilar upper arm width, upper arm circumference and five skin-fold thickness measures." (PMID 20442772, 2010). "A cluster of SNPs (single nucleotide polymorphism) located in the first intron of FTO was found to be significantly associated with obesity-related traits, such as body mass index, hip circumference, and body weight." (PMID 21103374, 2010). "For example, a GWAS for fat mass and obesity identified the strongest association in the first intron of FTO gene." (PMID 19562039, 2009).
Obesity (continued). "Polymorphism in the FTO gene is strongly associated with obesity, but little is known about the molecular bases of this relationship." (PMID 19860904, 2009). "Recent studies have identified two strong obesity candidate genes, the fat mass and obesity associated (FTO) and melanocortin 4 receptor (MC4R) –18." (PMID 19390624, 2009). "The evidence presented here suggests that DED and FTO simply combine to increase the risk of obesity in an additive manner." (PMID 19259258, 2009). "The obesity associated FTO variant rs9939609 was genotyped in the ULSAM cohort, a longitudinal cohort of adult men." (PMID 20003232, 2009). "Recently, genome-wide association studies have led to rapid progress in our understanding of the genetic basis of various common diseases and a new candidate gene for obesity has been identified, the fat mass and obesity associated gene, FTO." (PMID 20003232, 2009). "In genome-wide association studies (GWAS) for type 2 diabetes, a single nucleotide polymorphism (SNP) within intron 1 of the fat mass and obesity-associated (FTO) gene was found to be associated with an increased risk of obesity." (PMID 19680540, 2009). "Common FTO (fat mass and obesity associated) gene variants have recently been strongly associated with body mass index and obesity in several large studies." (PMID 20003232, 2009). "Variation in the fat mass and obesity associated (FTO) gene has been reproducibly associated with body mass index (BMI) and obesity in populations of White European origin." (PMID 19265514, 2009). "Genome-wide association studies of type 2 diabetes have also suggested an involvement of FTO in the disease pathogenesis, although this is likely to reflect the association with the associated phenotype of obesity." (PMID 19265514, 2009). "Our data provide functional evidence that FTO is a causal gene underlying the association of SNPs within intron 1 of FTO with obesity." (PMID 19680540, 2009). "Recent genome-wide association studies have shown that variants in the fat mass and obesity-related gene (FTO) are significantly associated with obesity in populations of European origin." (PMID 19461885, 2009). "Most of the previous studies on the FTO gene variants are cross-sectional, leaving the longitudinal pattern of the associations between obesity and age-specific genetic effects poorly studied." (PMID 20003232, 2009). "Different versions of the human gene FTO strongly correlate with BMI; the FTO gene with significant polymorphic variation has been identified in several papers as a candidate gene predisposing to obesity." (PMID 19878575, 2009). "We have previously validated the association between the rs9939609 variant within FTO and obesity measures, and interestingly, an interaction with physical activity was demonstrated to differentiate the degree of body fat accumulation between genotype groups." (PMID 18682847, 2008). "Recently two studies have found associations of several single nucleotide polymorphisms (SNPs) in FTO with body mass index (BMI) and obesity, particularly rs1421085, rs17817449, and rs9939609." (PMID 18218107, 2008). "A potential practical example is the FTO gene, whose association with obesity and related phenotypes was identified in three independent GWA studies in French, German, and British populations." (PMID 19112512, 2008). "A potential candidate underlying genetic susceptibility to MetS is the FTO (fat mass and obesity associated) gene, encoding the human analogue of fused toes in mice." (PMID 18339204, 2008). "The FTO rs9939609 SNP is of particular interest since it was found to be associated with obesity through independent studies of large Caucasian populations." (PMID 18339204, 2008). "Despite considerations regarding sample size however, the results reaffirm the established association between the FTO rs9939609 A allele with obesity in past findings." (PMID 18339204, 2008).
Obesity (continued). "Further studies are needed to clarify the functional relationship of FTO with obesity susceptibility." (PMID 18218107, 2008). "The first genome wide association study (GWA) for early onset extreme obesity recently revealed highly significant association of six strongly linked SNPs in intron one of FTO with obesity." (PMID 18799002, 2008). "We focused on physical activity as an environmental risk factor, and on the GWA identified obesity variants in FTO (rs9939609) and near MC4R (rs17782313) as genetic risk factors." (PMID 18682847, 2008). "Human population genetic studies have found FTO single nucleotide polymorphisms (SNPs) to be associated with type 2 diabetes and obesity." (PMID 18339204, 2008). "We have previously identified strong association of six single nucleotide polymorphisms (SNPs) in FTO (fat mass and obesity associated gene) to early onset extreme obesity within the first genome wide association study (GWA) for this phenotype." (PMID 18799002, 2008). "As such, variants in the FTO gene confer a similar magnitude of risk of obesity to children as to their adult counterparts and appear to have a global impact." (PMID 18335027, 2008). "The rs9939609 T>A single-nucleotide polymorphism (SNP) in the FTO gene has previously been found to be associated with obesity in European Caucasian samples." (PMID 18339204, 2008). "First, genetic polymorphisms in the vitamin D receptor, insulin-induced gene 2 (INSIG2), and FTO genes (fat mass and obesity associated genes) have been linked to obesity and metabolic disorders." (PMID 18335103, 2008). "Recently an association was demonstrated between the single nucleotide polymorphism (SNP), rs9939609, within the FTO locus and obesity as a consequence of a genome wide association (GWA) study of type 2 diabetes in adults." (PMID 18335027, 2008). "A now well-established link to obesity includes variants within the first intron of the fat mass and obesity associated gene (FTO)." (PMID 18682847, 2008). "It is therefore possible that impaired cerebrocortical insulin response at least partly accounts for the implication of FTO variants on obesity." (PMID 18799002, 2008). "For example, FTO associations with physical activity related body fat accumulation and obesity related traits were found in studies having large sample sizes." (PMID 18218107, 2008). "We conclude that variation in the first intron of FTO is a risk factor for early onset obesity while its impact on weight loss or serum levels of blood glucose, triglycerides and cholesterol (LDL, HDL) is not detectable in our study group." (PMID 18799002, 2008). "The results from this study indicate that FTO can have a substantial effect on obesity risk between individuals close in age, having similar rearing environments, and sharing half their genes identical by descent." (PMID 18218107, 2008). "The results of this study strongly replicate and extend those from previous reports of an association between FTO and human obesity." (PMID 18218107, 2008). "The FTO gene encodes the fat mass and obesity associated protein, Fatso and has been recently shown to be a 2-Oxoglutarate–Dependent Nucleic Acid Demethylase." (PMID 18335027, 2008). "In the case of FTO, it probably reflected the fact it was associated with type 2 diabetes through its effect on the correlated phenotype of obesity; the phenotype correlation varied across different studies." (PMID 17786212, 2007). "Genetic variants in the FTO (fat mass and obesity associated) gene have been associated with an increased risk of obesity." (PMID 17996046, 2007). "For example, one gene associated with T2DM, fat mass and obesity associated gene (FTO), also showed an association with obesity-associated quantitative traits in an independent study." (PMID 19662211, 2007). "It subsequently transpired that FTO exerts its effect on T2D risk through adiposity and has since been established as an obesity gene." (PMID 17897328, 2007).
Obesity (continued). "Recent studies have highlighted the role of N6-methyladenosine (m6A) RNA modifications in MM progression; however, the function of the m6A demethylase fat mass and obesity-associated protein (FTO) remains unclear." (PMID 41668508, 2026). "A number of studies have been performed on the association between obesity and the FTO gene." (PMID 41567168, 2026). "Dysregulation of the FTO gene has been linked to various conditions, including obesity, T2D, and PCOS, which contributes to these conditions through its effect on body weight and BMI, in addition to its impact on metabolic factors like IR, insulin sensitivity, serum glucose, and hyperandrogenemia." (PMID 40486662, 2025). "Enrichment of A. muciniphila leads to generate more indole‐3‐lactic acid (ILA) to upregulate the expression of 12α‐hydroxylase (CYP8B1) via fat mass and obesity‐associated protein (FTO)/ N6‐methyladenosine (m6A)/YTHDF2 manner, thereby facilitating cholesterol converts to cholic acid (CA)." (PMID 39888270, 2025). "Initially, a meta‐analysis of FTO gene polymorphism mainly focused on obesity." (PMID 40391584, 2025). "The FTO variant (rs9939609) is the most closely associated locus GWAS for BMI in 7,861 Koreans including ethnic Malays living in Singapore, this variant is strongly related with obesity." (PMID 39981080, 2025). "Since FTO was first discovered to be associated with fat mass and obesity, a large number of studies have demonstrated that FTO plays critical roles in metabolic diseases, such as obesity and diabetes, and cardiovascular diseases." (PMID 40234389, 2025). "The FTO gene was initially identifying through a genome‐wide association study, which identified it as an independent genetic risk factor uniquely contributing to the development of obesity." (PMID 41324103, 2025). "This hypothesis was substantiated by the findings that fat mass and obesity-associated (FTO) demethylate RNA m6A, and that RNA methylation modifications are reversible." (PMID 40282280, 2025). "A study in rats showed that stressful conditions can stimulate the expression of miR‐124‐3p, which regulates the fat mass‐ and obesity‐associated (FTO) enzyme, thereby affecting FTO‐dependent m6A methylation of neural plasticity gene mRNAs in the hippocampus (Roy, Ochi, and Dwivedi 2022)." (PMID 39367666, 2025). "Additionally, individuals carrying specific FTO risk alleles (eg, rs9939609) show DNA methylation changes at loci associated with obesity, though a direct link between m6Am levels and DNA methylation in these individuals has not been explored yet." (PMID 40862085, 2025). "The alteration of certain obesity-promoting genes (e.g., FTO and peroxisome proliferator-activated receptor gamma gene (PPARγ)) and anti-obesity genes (e.g., LEP, GLP-1R, and POMC) may be associated with obesity." (PMID 40868241, 2025). "In East Asians, certain alleles related to type II diabetes and obesity (such as the FTO gene) could indirectly increase SO risk via obesity." (PMID 40718355, 2025). "The m6A demethylase FTO (fat mass and obesity-associated protein) is known to affect body weight, but its systemic context and underlying mechanisms remain unclear." (PMID 40634669, 2025). "Moreover, excessive protein intake, combined with the upregulation of the fat mass and obesity-associated gene (FTO) and a deficiency of breast milk-derived microRNAs from lactation, disrupts the proper regulation of FTO and Wnt pathway components." (PMID 40429638, 2025). "The fat mass and obesity-associated gene (FTO), initially identified by Genome-Wide Association Studies (GWAS) as being associated with obesity related traits, disease susceptibility, and metabolic processes, was later found to be implicated in various cancers." (PMID 40722726, 2025). "Several significant risk loci associated with CAVS, such as those in LPA and FTO, are related to lipid metabolism and obesity, respectively, which could be offset by maintaining ideal CVH." (PMID 41206526, 2025).
Obesity (continued). "Previous research has demonstrated that FTO SNP influences individuals’ susceptibility to obesity through subtle effects on diet and energy intake, and subsequently leads to a range of obesity-related complications, such as type 2 diabetes." (PMID 40316995, 2025). "This genetic association highlights the potential role of FTO in obesity-related cancer risk." (PMID 40630163, 2025). "A recent study identified that the allelic frequencies of the fat mass and obesity-associated (FTO) polymorphism FTO rs9939609 (A) and the leptin receptor polymorphism LEPR rs1137101 (223R) are correlated with an elevated risk of obesity among the Egyptian population." (PMID 41423640, 2025). "Human GWAS paradoxically linked FTO SNPs to both lean mass and sarcopenia/obesity." (PMID 40055326, 2025). "Conversely, the FTO gene (T;T) genotype lowers the risk of developing T2D and obesity by 1.5 times." (PMID 39925495, 2025). "The fat mass and obesity-associated (FTO) gene, originally named “Fatso” due to its abbreviation from “FT” (short for “Fused Toes”), referring to limb deformities observed in rats lacking this gene, has attracted renewed attention in recent years due to its association with weight gain." (PMID 41141248, 2025). "Notably, the fat mass and obesity-associated (FTO) gene, which encodes an m6A demethylase, has been strongly associated with obesity and metabolic disorders in genome-wide association studies (GWAS)." (PMID 39984825, 2025). "Variations in the FTO gene may influence the risk of obesity, which is a known risk factor for pre-eclampsia and cardiovascular complications." (PMID 41234028, 2025). "Obesity; weight; overweight; FTO gene (fat mass and obesity-associated gene)." (PMID 40797480, 2025). "However, our understanding of the fundamental mechanisms underlying genetic risk for obesity is limited and controversial even for FTO, with the most prominent effects on BMI." (PMID 41006818, 2025). "This study might suggest that the FTO rs9939609 AA genotype is associated with increased obesity in both pre and post-menopause women with BC; it could be more clarified with a large sample size." (PMID 40630163, 2025). "FTO, which is regarded as the gene with the strongest association with obesity that has been discovered thus far, could potentially be a determinant of NAFLD-associated HCC." (PMID 40316995, 2025). "Thus, the present study evaluated the association between dietary patterns and cardiometabolic risk factors in children with fat mass and obesity associated (FTO) gene polymorphism." (PMID 40906427, 2025). "The fat mass and obesity-associated (FTO), which is expressed in the hypothalamus, may regulate the m6A methylation of its target genes, influencing GnRH expression in the hypothalamus during puberty onset." (PMID 41244054, 2025). "Association of FTO genotypes with obesity in case and healthy control." (PMID 40630163, 2025). "Interestingly, most of the GWAS investigations on different populations indicate FTO gene SNPs as a common risk factor for various obesity-related traits." (PMID 40024983, 2025). "The epigenetic modulation exerted by breastfeeding seems to also affect other genes involved in energy metabolism, such as fat mass and obesity-associated (FTO) gene, Retinoid X Receptor Alpha (RXRA), and human peroxisome proliferator-activated receptor gamma (PPAR-γ) gene." (PMID 40004988, 2025). "FTO initially became known as the most significant genetic factor associated with human obesity." (PMID 40022434, 2025). "In addition to the widely studied rs9939609 variant of the FTO gene, other SNPs such as rs8050136 and rs1558902 have also been shown to be significantly associated with obesity-related traits." (PMID 40630163, 2025).